MIR3179-2 (microRNA 3179-2)
Synonyms: hsa-mir-3179-2
Gene: MicroRNA gene on chromosome 16 (16,300,159 to 16,300,242, forward strand). Ensembl gene ENSG00000257381.
Gene Ontology:
Biological process: miRNA-mediated post-transcriptional gene silencing
Cellular component: RISC complex
Homologues: Paralogues in human: MIR3179-1 (100% identical), MIR3179-3 (100% identical), MIR3179-4 (100% identical).